MMP2 (matrix metallopeptidase 2)
Diseases named in the same sentence as MMP2 in open-access papers (continued):
Sharing a sentence is not in itself a finding about the gene and the disease.
myopia (continued). "This study aims to investigate the effect of citicoline on the expression of MMP-2, TGF-β1, and Ki-67 as fibroblast cell-proliferating markers, and on the thickness of scleral tissue of rat models for myopia." (PMID 36289864, 2022). "The aim of this study is to demonstrate the effect of citicoline on the expression of MMP-2, TGF-β1, and Ki-67, and on the thickness of scleral tissue of a rat myopia model." (PMID 36289864, 2022). "A decrease in resveratrol-treated eyes has been observed in myopia-related tissue remodeling proteins and the expression of inflammatory cytokines (NFκB, TGF-β, MMP2, TNFα, IL-6, and IL-1β)." (PMID 35889930, 2022). "The secretion of TIMP-1, MMP2, bFGF, and IGF-1, which were involved in pathological myopia, were detected with ELISA assay in ARPE-19 cells treated with 1 μg/mL of insulin for 24 or 72 h." (PMID 34001063, 2021). "Atropine and diacerein suppressed levels of the myopia-related TGF-β1 and MMP-2 while increasing type I collagen expression." (PMID 34285659, 2021). "In this study, the hamsters in which myopia was induced by the MFD model, showed higher MMP2 and TGF-β levels and a lower collagen I level, similar to the findings obtained in previous studies on myopic eyes." (PMID 34287272, 2021). "Our results suggest that orally administered LF inhibited MMP-2 activation during LIM, followed by a suppression of myopia development." (PMID 33291388, 2020). "Many investigators believe that MMPs and TIMPs, particularly MMP-2 and TIMP-2, are potential targets to inhibit myopia development." (PMID 32596291, 2020). "We previously measured TGF-β2 and MMP-2 levels in the vitreous of patients with high myopia and found that the MMP-2 level was elevated and strongly correlated with the TGF-β2 level in high myopia." (PMID 30665391, 2019). "Recent study showed that downregulation of MMP2 expression levels and increased TIMP2 levels accompanied the pirenzepine-induced suppression of myopia in guinea pig44." (PMID 28900109, 2017). "The reported changes include transforming growth factors (TGF-β 1–3) and MMPs (MMP-2 and MMP-14) suggesting that growth factors and MMPs are critical components in scleral remodeling pathways during myopia development." (PMID 27870875, 2016). "Estrogen has been shown to upregulate MMP-2 and/or MMP-9 in human ocular cells, and MMP-2 upregulation was suggested as part of the scleral remodeling process in myopia development." (PMID 21921981, 2011). "The combination of bilberry extract and DHA demonstrates significant efficacy in controlling myopia progression through multiple mechanisms, including upregulation of Chrnb4 gene expression, modulation of the TGF-β/MMP-2/TIMP-1 signaling pathway, and enhancement of dopamine levels." (PMID 40534703, 2025). "Besides, MMP-2 and tissue inhibitor of metalloproteinase 2 (TIMP-2) produced by fibroblast are closely related to the ECM degradation of sclera during myopia progression." (PMID 41169617, 2025). "In this study, we found that after 2 and 4 weeks of myopia induction, the expression of TGF-β1, COLI, and TIMP2 decreased compared with the levels of normal guinea pigs, whereas the expression of E-cadherin and MMP2 increased." (PMID 40216914, 2025). "Future work should include the evaluation of latent versus active TGF-β pools, as well as endogenous activators such as MMP2, integrins (e.g., αvβ6), or thrombospondin-1, to more precisely model the endogenous regulation of TGF-β activity in the progression of myopia." (PMID 40862775, 2025). "Various factors have been shown to contribute to the development of myopia, including TGF-β, matrix metalloproteinase-2 (MMP2), and collagen I. TGF-β is expressed in tissues of the eye and remodels the scleral extracellular matrix (ECM), which reduces collagen production." (PMID 35889930, 2022).
myopia (continued). "In contrast, the control rats (negative control, n = 5) and rat models for myopia with a citicoline dosage of 100 mg/kg BW/day (n = 5) and 200 mg/kg BW/day (n = 5) lack evidence of MMP-2-positive staining." (PMID 36289864, 2022). "The immunohistochemical staining for MMP-2 expression showed that the rat models for myopia without treatment (positive control, n = 5) display a high number of MMP-2-positive stains." (PMID 36289864, 2022). "Induction of myopia leads to increased TGF-β expression and continues to activate MMP-2 expression." (PMID 36242032, 2022). "Citicoline is able to decrease MMP-2 expression and fibroblast proliferation and increase TGF-β1 expression and scleral tissue thickness significantly in the scleral tissue of rat models for myopia." (PMID 36289864, 2022). "AL was not consistently or substantially affected by MMP-2 in the PL, indicating myopia formation was possibly a localized process." (PMID 32596291, 2020). "Thus, LF administration inhibited LIM-induced proteolytic activity of MMP-2 and MMP-9, followed by the suppression of myopia development." (PMID 33291388, 2020). "Reducing scleral MMP2 could alleviate the reduction of COL1 accumulation and retard myopia progression in mice." (PMID 32719611, 2020). "We demonstrated that over-expression of HOXA9 in RPE cells could increase pro-myopia substances including TGF-β, FGF2, IGF1R and MMP2." (PMID 30674274, 2019). "Although there is no specific molecular marker for myopia, several molecules have been reported to be associated with myopia, which include TGF-β, FGF2, IGF signaling, HGF and MMP2." (PMID 30674274, 2019). "These are in MMP2 for refractive error and in MMP3 and MMP9 for common myopia." (PMID 23077567, 2012). "Furthermore, we demonstrated that pharmacological inhibition of choroidal MC degranulation effectively attenuated myopia progression and suppressed scleral remodeling by preventing the downregulation of COL1A1 and the upregulation of matrix metallopeptidase 2 (MMP-2)." (PMID 41222199, 2025). "The expression of MT1-MMP and MMP-2 was also up-regulated in guinea pigs in the LIM group in the present study, which may suggest that this mechanism is also active in the guinea pig lens-induced myopia models." (PMID 36652495, 2023). "This may explain why ROS induced in photoreceptors further upregulated the expression of myopic molecular marker (MMP2) in co‐cultured RPE cells in our study, and therefore indicate how HK2‐related glucose metabolism might be related to high myopia development." (PMID 37746666, 2023). "We propose that citicoline reduces MMP-2 expression and fibroblast proliferation and increases TGF-β1 expression and scleral tissue thickness and, therefore, may be useful for inhibiting the progression of myopia." (PMID 36289864, 2022). "MMP-2 and TIMP-2 could affect scleral ECM and mediate the scleral remodeling during myopia." (PMID 35783515, 2022). "This might imply that MMP-2 in the AH of myopia patients is not directly dependent on the MMP-2 in the PL." (PMID 32596291, 2020). "Here we presented the changes in mRNA expression levels of three genes (MMP2, TIMP2, and TGFB2), all known to participate in extracellular matrix organization, at five regions of the cornea and sclera in chickens developing high myopia and astigmatism induced by form deprivation." (PMID 28900109, 2017). "However, when the role of the rare variants in high myopia was explored with DNA sequence analysis for the exons of MMP2 in small numbers of patients with high myopia, no fruitful results were found." (PMID 23378725, 2013). "Our results imply that MMP2 may not play a major role in high myopia in the Han Chinese population." (PMID 23378725, 2013). "Interestingly, a recent study have shown that low doses of TIMP-2 promote MMP-2 activation, whereas high doses inhibit its activation, reduce collagen degradation, and shorten the AL, suggesting that TIMP-2 supplementation may be helpful in controlling myopia progression." (PMID 39430251, 2024).
myopia (continued). "The significant correlations of choroidal thickness with MMP-2 and TIMP-2, but not with VEGF-A further suggests that the mechanisms resulting in thinning of choroid observed in high myopia may be related to mechanical factors rather than ischemic factors." (PMID 31673022, 2019). "The negative correlation of MMP-2, and corresponding positive correlation with TIMP-2, with choroidal thickness seen in our study suggests that this postulated degradation of Bruch’s membrane may also be related to the progressive thinning of the choroid seen in eyes with high myopia and MMD." (PMID 31673022, 2019).
endometriosis (72 papers, 2008 to 2026). The growth of functional endometrial tissue in anatomic sites outside the uterine body. "MMP2 has been found to be associated with changes in steroid hormones in endometriosis sera and peritoneal fluid." (PMID 39796199, 2025). "MT1-MMP is involved in the activation of proMMP2, and it is often linked to increased activation and expression of MMP2 in cases with endometriosis versus controls." (PMID 37893104, 2023). "In murine model of endometriosis, inhibition of MMP-2 exhibited decreased numbers of endometriotic lesions along with reduced VEGF expressions, suggesting occurrence of endometriosis and associated angiogenesis through MMP-2 activities." (PMID 27695098, 2016). "Until now few studies have documented regression of endometriosis upon total inhibition of MMPs in mouse model and CAM model of endometriosis, however, we report for the first time the specific role of MMP-2 in endometriosis-associated angiogenesis." (PMID 27695098, 2016). "Several studies have shown that certain genes and proteins in the endometrium, including p-ERK, DJ-1 and MMP-2, are involved in endometriosis-associated proliferation, migration, invasion and angiogenesis." (PMID 23855590, 2013). "Recent studies have underlined the critical role of MMP-2 in endometriosis." (PMID 23855590, 2013). "In a mouse model, Ureoplasma urealyticum infection promotes endometriosis by enhancing inflammatory mediators and MMP-2 expression via TLR2 signaling." (PMID 40508002, 2025). "Increased MMP-2 expression in the ectopic endometrium can indicate aggressive progression of endometriosis." (PMID 38255200, 2024). "Tissue remodeling is promoted by MMP-2 and MMP-9, which play a role in the generation of adhesions, the fibrous tissue that can cause tissues to adhere together in endometriosis." (PMID 38398530, 2024). "In female patients suffering from endometriosis, resveratrol showed potential in reducing the invasiveness of endometriosis due to reduced expression of MMP-2 and MMP-9." (PMID 38612425, 2024). "The relative area of MMP-2 expression in glands was a statistically significant difference (p < 0.05) during stage IV of extragenital endometriosis in comparison with the control (p = 0.021)." (PMID 38255200, 2024). "Another study has demonstrated the opposite result: a decrease in MMP-2 in the eutopic endometrium of women with endometriosis." (PMID 38255200, 2024). "It was found that MMP-2 expression in endometrial heterotopias and the endometrium increased at all stages of endometriosis." (PMID 38255200, 2024). "Research has consistently demonstrated that women with endometriosis have higher levels of MMP-2 and MMP-9 expression in their blood, peritoneal fluid, and endometrium compared to healthy individuals." (PMID 38398530, 2024). "Specifically, it was observed that the administration of RiDE in rats with endometriosis was able to restore MMP2 and MMP9 values to normal conditions." (PMID 38398530, 2024). "Another study showed up-regulation of MMP-2 activity by tissue inhibitor of metalloproteinases 2 (TIMP-2) in early endometriosis and an inhibitory effect of curcumin on endometriosis." (PMID 37375677, 2023). "Endometrium and peritoneal fluid from women with endometriosis were shown to have elevated levels of MMP-2 and -3." (PMID 36551177, 2022). "MMP-2 is a collagenase-degrading collagen IV, the principal component of basement membranes, and is significantly elevated in the urine of patients with endometriosis, compared to healthy women." (PMID 35334511, 2022). "Meanwhile, in subjects suffering from endometriosis, reduced levels of autophagy were accompanied by elevated MMP-2 expressions." (PMID 34967693, 2022). "This suggests a possible role of these proteins in establishment and development of adenomyosis by activation of MMP2, which has been shown to be upregulated in patients with adenomyosis and endometriosis." (PMID 35453827, 2022).
endometriosis (continued). "The over-expression, enhanced secretion, and activity of MMP2 and MMP3 has previously been implicated in pathogenesis of endometriosis." (PMID 36551177, 2022). "Particularly, MMPs are involved in cyclic changes of the endometrial structure and thickness during menstruation and dysregulation of MMP2, and MMP3 has previously been implicated in the pathogenesis of endometriosis." (PMID 36551177, 2022). "A recent study demonstrated that physiological changes, including adhesion, in endometriosis involve abnormal matrix remodeling, which is affected by proteolytic enzymes, such as MMP-2." (PMID 35334511, 2022). "Several studies have reported that the levels of MMPs are elevated in the ectopic tissue, peritoneal fluid, or sera of patients with endometriosis, especially MMP2 and MMP9." (PMID 34827737, 2021). "MMP-2 is one of the members of the MMP family proteins that play an important role in the formation of endometriosis." (PMID 33750407, 2021). "The role of MMP2 in endometriosis is still matter of debate: the available data on its expression in uterine endometrial tissue in women with and without endometriosis remains contradictory." (PMID 32325785, 2020). "According to in vivo results, the expression of MMP2 seems to be unaffected by TNFα treatment, both in HESCs prepared from healthy patients (HE-HESCs) and from women with endometriosis (EE-HESCs)." (PMID 32325785, 2020). "In order to clarify the role of metalloproteases and their inhibitors in endometriosis development, MMP2, MMP3, MMP10, TIMP1, and TIMP2 expression was measured in healthy and eutopic endometrium, in OMA and DIE lesions." (PMID 32325785, 2020). "In the current study, we have detected elevated MMP-2 expression in both ectopic and eutopic tissues of endometriosis patients compared to the normal control group." (PMID 31037923, 2019). "Firstly, by enzyme linked immunoabsorbent assay, we found that IL-34, VEGF, MMP-2 and MMP-9 were increased in the sera of patients with endometriosis." (PMID 31727934, 2019). "Peritoneal fluids and sera from endometriosis patients were also shown to contain higher levels of MMP-2 than those from controls." (PMID 31636643, 2019). "Collectively, U. urealyticum infection promotes the development of endometriosis by increasing inflammatory mediators, adhesion molecules, and MMP-2 expression in PMCs through TLR2 signaling." (PMID 31636643, 2019). "This study shows that Rg3E significantly downregulates MMP2 and MMP9, blocking a significant pathogenic pathway of endometriosis." (PMID 29247225, 2017). "Our study reveals the involvement of COX-2-PGE2-pAKT-mediated signaling pathways in regulation of MMP-2 activity and subsequent angiogenesis in endometriosis." (PMID 27695098, 2016). "In conclusion, our study establishes the involvement of MMP-2 activity via COX-2-PGE2-pAKT axis in promoting angiogenesis during endometriosis progression." (PMID 27695098, 2016). "PGE2, a pro-angiogenic factor for endometriosis, is involved in elevating MMP-2 activity in endothelial cells." (PMID 27695098, 2016). "Peritoneal fluids and serum of endometriosis patients contained higher levels of MMP-2 than those of unaffected patients." (PMID 27695098, 2016). "In accordance, positive correlation of MMP-2 with 17β-E2 levels in the peritoneal fluids of endometriosis patients has been documented." (PMID 27695098, 2016). "Our data suggest the role of MMP-2 through PGE2-mediated pathway for the promotion of angiogenesis in endometriosis." (PMID 27695098, 2016). "Herein, we address the importance of MMP-2 in relation to pathological angiogenesis during progression of endometriosis." (PMID 27695098, 2016). "In accordance, previous study from our laboratory has found reduced interaction between TIMP-2 and MMP-2 during MMP-2 activation in mouse model of early endometriosis." (PMID 27695098, 2016).